ARL4C (ARF like GTPase 4C)
Diseases named in the same sentence as ARL4C in open-access papers (continued):
Sharing a sentence is not in itself a finding about the gene and the disease.
tumor (continued). "We did not observe any significant changes in the levels of secreted TGFβ1 when Arl4c was knocked down in the cancer cells themselves, further confirming that this effect of Arl4c on promoting tumor stemness and drug resistance depends on its role in PSCs." (PMID 34849465, 2021). "ARL4C has been shown to be localized to membrane protrusions of non-tumor cells, such as IEC6 and Madin-Darby canine kidney (MDCK) cells." (PMID 34590580, 2021). "Another study with gastric cancer showed that the expression of ARL4C was abnormal and the molecule was involved in tumor cell growth and cell migration." (PMID 33194732, 2020). "Recent research has revealed that ARL4C is frequently overexpressed in colorectal and lung cancers and that it plays an important role in tumor progression by promoting the proliferation, migration, and invasion of cancer cells." (PMID 31366141, 2019). "In the tumor lesions, ARL4C mRNA was elevated and this data is consistent with our previous immunohistochemical data." (PMID 27835592, 2016). "When SAS cells were grown in 3D culture conditions with Matrigel, knockout of ARL4C reduced the spherical area of the tumor by half." (PMID 27835592, 2016). "In tumor lesions of ARL4C-positive lung SCC, 5hmC was frequently detected and DNA methylation in the 3’-UTR of ARL4C gene was lower than in non-tumor regions, which were consistent with the Cancer Genome Atlas dataset." (PMID 27835592, 2016). "Immunohistochemical analysis showed that 5hmC was observed in approximately 35% and 74% of the nuclei of ARL4C-negative and ARL4C-positive tumor lesion cells, respectively." (PMID 27835592, 2016). "In the tumor lesions, ARL4C mRNA was elevated and DNA methylation status, in both the promoter region and the 3’-UTR, was decreased compared to those regions in non-tumor regions." (PMID 27835592, 2016). "Bisulfite pyrosequencing data showed that ARL4C DNA methylation levels are significantly reduced in the 3’-UTR in tumor lesions compared to non-tumor regions." (PMID 27835592, 2016). "It is of note that ARL4C was strongly expressed in some cases from the advancing areas of tumor lesions, which are invading in the surrounding stroma." (PMID 27835592, 2016). "Notably, ARL4C expression progressively increased with advancing tumor stage and lymph node involvement." (PMID 41328352, 2026). "Remarkably, combined ARL4C knockdown and oxaliplatin treatment completely suppressed tumor growth, suggesting that targeting ARL4C could significantly enhance oxaliplatin efficacy in CRC patients." (PMID 41328352, 2026). "Notably, ARL4C overexpression markedly accelerated subcutaneous tumor growth and completely abrogated the antitumor effects of oxaliplatin." (PMID 41328352, 2026). "Further, immunoprecipitation assays showed that oxaliplatin treatment decreased ARL4C ubiquitination levels compared to controls, suggesting that tumor cells may attenuate ARL4C degradation to resist oxaliplatin cytotoxicity." (PMID 41328352, 2026). "Notably, ARL4C overexpression completely reversed oxaliplatin-induced tumor suppression, mirroring our in vitro findings and underscoring ARL4C as a potential driver of oxaliplatin resistance." (PMID 41328352, 2026). "The results consistently confirmed ARL4C's role in promoting tumor proliferation." (PMID 41328352, 2026). "Currently, the majority of research on ARL4C is centered on the tumor immune microenvironment." (PMID 38404591, 2024). "The expression of ARL4C in cancer-associated stromal cells was notably higher, indicating that ARL4C may exert multiple effects on the tumor microenvironment." (PMID 38404591, 2024). "Furthermore, recent studies have demonstrated the significant role of ARL4C in mediating immune-inflammatory responses within the tumor microenvironment." (PMID 38404591, 2024). "ARL4C-targeted therapy and prediction hold promise as a potential approach for tumor treatment." (PMID 38178862, 2023).
tumor (continued). "In addition, the involvement of ARL4C in the tumor immune microenvironment has expanded the concept of ARL4C-targeted immunotherapy." (PMID 38178862, 2023). "We contend that the existing research fails to fully elucidate the intricate mechanism of ARL4C in various tumors and its association with the tumor immune microenvironment." (PMID 38178862, 2023). "Our findings demonstrate that ARL4C exhibits extensive localization within the plasma membrane and cytosol across various tumor cell lines, suggesting that its broad distribution may be a fundamental prerequisite for its functional roles." (PMID 38178862, 2023). "ARL4C has been shown to be highly expressed in various tumor cells." (PMID 38178862, 2023). "ARL4C is a potential therapeutic target because tumor growth is suppressed by siRNA against ARL4C." (PMID 37237373, 2023). "The percentages of ARL4C expression cases in the non-tumor regions and tumor lesions are shown." (PMID 34590580, 2021). "Furthermore, we identified the ARL4C expression in frozen tumour and adjacent mucosa tissues of 12 GC patients at the Xijing Hospital of Digestive Diseases (Cohort II) by Western blot analysis." (PMID 33724652, 2021). "Based on these studies, the function of Arl4c shows tumor specificity and pathology specificity." (PMID 34849465, 2021). "Given that ARL4C was involved in regulating the biological behaviours of various tumours, we examined whether its expression might affect the malignant phenotypes of GC cells by in vitro and in vivo experiments." (PMID 33724652, 2021). "Previous studies showed that several relevant downstream signals, such as ERK, JAK, and AKT, might be involved in tumor-promoting effects of ARL4C." (PMID 33194732, 2020). "However, immunohistochemical analysis showed that ARL4C was highly expressed in tumor lesions where 5hmC levels were also high." (PMID 27835592, 2016). "Furthermore, ARL4C expression in the cancer stromal cells was stronger, suggesting that ARL4C expression in cancer stromal cells may have various effects on the tumor microenvironment." (PMID 37237373, 2023). "Therefore, ARL4C may serve as a potential therapeutic target for overcoming resistance to other types of anti-tumor drugs and needs to be further explored." (PMID 38178862, 2023). "We found that ARL4C expression was related to the infiltration of various immune cells, thus suggesting that ARL4C may play a role in selecting immune cells that infiltrate the tumor microenvironment in KIRC tumors through a specific mechanism." (PMID 35774359, 2022). "In addition, tumor cells surrounding peritumoral lymphatic vessels were also decreased, which is consistent with our hypothesis that ARL4C is required for cell invasive activity." (PMID 34590580, 2021). "However, overexpression of ARL4C increased SOX2 in tumor cells." (PMID 33403039, 2021). "Since ARL4C regulates cellular migration and invasion through the activation of Rac and the inactivation of Rho, its overexpression in the peripheral areas of tumor lesions could promote invasiveness of cancer cells." (PMID 27835592, 2016). "Furthermore, since ARL4C knockdown by in vivo siRNA suppressed xenograft tumor formation, ARL4C might represent a novel therapeutic target for cancers with ARL4C overexpression." (PMID 27835592, 2016). "ARL4C knockdown increased epithelial marker E-cadherin while decreasing mesenchymal markers N-cadherin and Vimentin, indicative of EMT suppression and tumor-suppressive effects." (PMID 41328352, 2026). "p < 0.0001) 10.2-fold increase in tumor (Mean ± SEM = 3.54 ± 0.13 log2TPM) compared to normal tissue (Mean ± SEM = 0.19 ± 0.18 log2TPM); ARL4C mRNA exhibited a significant (Adj." (PMID 41465326, 2025). "In summation, the molecules ZNF165, MXRA7, CEMIP, ARL4C, and CERCAM collectively represent prospective therapeutic nexus points in impeding tumor advancement." (PMID 39624211, 2024).
tumor (continued). "However, whether ARL4C is associated with the immune system and tumor immune microenvironment has not been studied." (PMID 38178862, 2023). "We also found that ARL4C and HOXC8 were upregulated, and FABP4, PCOLCE2, SERPING1, and SRPX were downregulated in tumor tissue compared to corresponding healthy tissue." (PMID 35664768, 2022). "ADP-ribosylation factor-like 4C (ARL4C) is a member of the small GTP-binding protein family and plays a role in tumor genesis and development." (PMID 36569303, 2022). "Both in TCGA and Oncomine databases, ARL4C and ARL13B were significantly up‐regulated in tumour tissues." (PMID 33724652, 2021). "In examining the capacity of ALDH1A3 knockdown to reverse tumor growth, we found that knockdown of ALDH1A3 attenuated the pro-oncogene effects of ARL4C overexpressed in GBM cells." (PMID 33403039, 2021). "Notably, ARL4C, a member of the ADP-ribosylation factor family of GTP-binding proteins, plays a critical role in the infiltration of immune cells into the tumor microenvironment, as well as in various aspects of cancer invasion and proliferation." (PMID 38404591, 2024). "The expression of ARL4C exhibited a significant and positive correlation with immune-related pathways such as TNF-α/NF-κB, INF-γ, INF-α, IL-6/JAK/STAT3, and hypoxia signaling pathways, thereby establishing a connection between ARL4C and tumor immunity." (PMID 38178862, 2023). "ARL4C, a Ras-GTP binding protein, was involved in various tumor progression processes 21,22." (PMID 33403039, 2021). "Arl4c was mainly expressed in the cytoplasm of tumor cells, and no Arl4c staining was found in PSCs." (PMID 34849465, 2021). "Analysis of TCGA and GTEx datasets revealed that ARL4C is highly expressed in tumor tissue than in non-diseased tissue." (PMID 34590580, 2021). "Tumor cells were observed in lymphatic vessels of peritumoral areas of control ASO-treated mice but not in those of ARL4C ASO-treated mice." (PMID 34590580, 2021). "Whereas ARL4C ASO-1316 did not reduce the size of the primary tumor in the pancreas, the ASO decreased the numbers of lymph node metastases and tended to improve the survival." (PMID 34590580, 2021). "Notably, ARL4C and MMP14 were expressed more highly in invasive cancer cells rather than in PanIN lesions, although IQGAP1 was thoroughly expressed in tumor lesions including PanIN area." (PMID 34590580, 2021). "These genes likely function as downstream effectors of STAT3 in GBM to regulate not only cell proliferation (e.g., GAS7, IGFBP2, MEOX2 and MXI1), and but also tumor-stroma interactions by modulating protein secretion (e.g., ANXA1, ARL4C, EMILIN1, EMP2, EXTL3 and PDIA4)." (PMID 29774125, 2018). "The methylation levels of the ARL4C promoter region (CpG islands) from tumor lesion tissue appeared to be reduced compared to non-tumor regions, although the difference was not significant." (PMID 27835592, 2016). "Although TET2 mRNA expression positively correlated to ARL4C mRNA expression and the expression of TETs mRNA inversely correlated to ARL4C DNA hypomethylation both in the 3’-UTR and promoter region, TET2 mRNA expression in tumor lesions was similar to non-tumor regions." (PMID 27835592, 2016). "ARL4C was also expressed in 42/57 (73.7%) of tumor lesions from tongue SCCs, but not in non-tumor regions of the tongue." (PMID 27835592, 2016). "Finally, in vivo experiments demonstrated that RAC1 knockdown markedly reduced ARL4C-driven pulmonary metastasis without significantly impacting subcutaneous tumor growth." (PMID 41328352, 2026). "Additionally, we observed a significant correlation between ARL4C and TMB in 12 tumor types." (PMID 38178862, 2023). "This study established the role of ARL4C in the initiation of premalignant lesions, tumor progression and development, and demonstrated the utility of ASO-1316 as a potential therapeutic agent for LC patients with ARL4C overexpression, regardless of mutation status." (PMID 33740988, 2021).
tumor (continued). "In addition, the TCGA dataset revealed that the function of TET2 might be important to induce ARL4C gene expression in lung SCC, but whether elevated TET2 expression in tumor lesions is required for the expression of ARL4C remains to be clarified." (PMID 27835592, 2016). "6-FAM–labeled ARL4C ASO-1316 was highly accumulated in tumor lesions but not in the neighboring normal tissues, indicating that ASO was incorporated into tumor lesions after systemic injection." (PMID 34590580, 2021). "Microarray profiles comparing GSLCs and non-stem tumor cells (NSTCs) isolated from primary human GBM (GBM-1) showed that 4 out of 100 members in the Ras-superfamily (RAB26, RAB27B, RAB6B and ARL4C) were significantly up-regulated in GSLCs (P < 0.05)." (PMID 33403039, 2021).
cancer (22 papers, 2016 to 2026). A tumor composed of atypical neoplastic, often pleomorphic cells that invade other tissues. "An intriguing question is what causes the increased level of ARL4C observed in various cancer cells." (PMID 39767779, 2024). "Background/Objectives: The changes in the level of small GTPase ARL4C are associated with the initiation and progression of many different cancers." (PMID 39767779, 2024). "In this work, we studied the biological role of small GTPase ARL4C associated with several types of cancer." (PMID 39767779, 2024). "The findings of this study provide further evidence supporting the association between ARL4C and immune regulation in these specific types of cancers." (PMID 38178862, 2023). "Subsequently, we observed a significant positive correlation between the expression of CD206, a biomarker for M2 macrophages, and α-SMA, a biomarker for cancer-associated fibroblasts (CAFs), with the expression of ARL4C in LIHC based on TCGA database analysis." (PMID 38178862, 2023). "This analysis revealed a strong association between ARL4C mRNA expression and methylation in various cancer types, with the exception of PCPG." (PMID 38178862, 2023). "To elucidate the association between ARL4C and the progression of various cancers, we assessed the mRNA levels of ARL4C across different pathological stages in 21 different cancer types." (PMID 38178862, 2023). "The proliferation of cancer cells is related to the nuclear localization of YAP/TAZ caused by ARL4C." (PMID 35774359, 2022). "Furthermore, ARL4C levels showed a positive correlation with cancer nodules (R = 0.487) and were associated with increased perineural invasion (59.8% vs. 4.5%)." (PMID 41328352, 2026). "In recent decades, several studies have linked the changes in the level of small GTPase ARL4C with various cancers and assumed that it may serve as a prognostic marker and a therapeutic target." (PMID 39767779, 2024). "Our research showed that small GTPase ARL4C associated with various cancers may serve as one of the regulators of the microtubule nucleation process both in normal and cancer cells." (PMID 39767779, 2024). "Consequently, we conducted a bioinformatics analysis to investigate the involvement of ARL4C in cancer development, examining its expression patterns, prognostic implications, and association with the immune microenvironment across various cancer types." (PMID 38178862, 2023). "Moreover, ARL4C expression in cancer stromal cells was associated with poorly differentiated adenocarcinoma components and higher TB grade." (PMID 37237373, 2023). "Furthermore, our investigation demonstrated that ARL4C was linked to TMB expression in 12 different types of cancers." (PMID 38178862, 2023). "Because TB grade has a strong influence on prognosis, the association between ARL4C expression and TB grade may have a strong influence on cancer metastasis." (PMID 37237373, 2023). "Consequently, we conducted an assessment of the mutation rate of ARL4C in cancer patients using the cBioPortal database." (PMID 38178862, 2023). "The observation that heightened ARL4C expression is linked to immune activation in cancer may offer promising prospects for ARL4C-targeted immunotherapy." (PMID 38178862, 2023). "In previous studies, high ARL4C expression was associated with poor prognosis in some carcinomas." (PMID 33092599, 2020). "Consistent with bioinformatics analyses, ARL4C expression was markedly higher in cancer tissues than in para-cancer tissues." (PMID 41328352, 2026). "Pan-cancer analyses further underscored the prognostic relevance of ARL4C across multiple malignancies." (PMID 41328352, 2026). "ARL4C is frequently overexpressed in various cancers due to aberrant activation of Wnt–β-catenin and EGF–RAS pathways." (PMID 39833546, 2025). "It seems that one or more functions of ARL4C acquire additional importance during cancer progression, which is reflected in the changes in its level in many cancer cells." (PMID 39767779, 2024).